CBX2 (chromobox 2)
Diseases named in the same sentence as CBX2 in open-access papers (continued):
Sharing a sentence is not in itself a finding about the gene and the disease.
acute myeloid leukemia (3 papers, 2022 to 2025). Acute myeloid leukemia (AML) is a group of neoplasms arising from precursor cells committed to the myeloid cell-line differentiation. "Mechanistically, in acute myeloid leukemia (AML) cell lines, CBX2 KD alters the expression of genes within the p38 MAPK pathway by inducing chromatin reorganization at these regulatory regions, thereby affecting AML cell survival." (PMID 40175347, 2025). "Similarly, sensitivity to CBX2 silencing was observed in primary acute myeloid leukemia samples." (PMID 35681235, 2022).
endometrial cancer (3 papers, 2015 to 2020). Primary or metastatic malignant neoplasm involving the endometrium (mucous membrane that lines the endometrial cavity). "Survival analysis showed that the higher the expression levels of lncRNAs C2orf48, PSAT1, KIF23, CCNE1, CDC25A and CBX2 in patients with endometrial cancer, the poorer the prognosis." (PMID 30581678, 2018). "When it comes to uterine mixed endometrial carcinoma, another distinctive pattern emerged and the most were the high mRNA expression of almost all CDCA members except CDCA3/7, and the missense mutation of NUF2, CDCA2/3/5, CBX2, CDCA7/8." (PMID 32913454, 2020). "A recent report that investigated the expression of CBX2 in human cancers showed initial evidence of an oncogenic role; however, the overexpression of both CBX2 and EZH2 in the basal-like subgroup indicates the importance of interplay between PRC1 and PRC2 in endometrial cancer." (PMID 26431491, 2015).
diffuse gastric adenocarcinoma (2 papers, 2020 to 2021). An adenocarcinoma arising from the stomach. "In Cho's gastric dataset, CBX2 was overexpressed in diffuse gastric adenocarcinoma (fold − change = 2.29 and P = 6.01E − 09) and gastric mixed adenocarcinoma (fold − change = 2.077 and P = 3.75E − 04)." (PMID 33344640, 2020).
gastric intestinal type adenocarcinoma (2 papers, 2020 to 2021). An adenocarcinoma of the stomach arising on a background of intestinal metaplasia. "D'Errico's gastric dataset showed CBX2 to be upregulated in gastric intestinal-type adenocarcinoma (fold − change = 4.485 and P = 1.7E − 09)." (PMID 33344640, 2020).
lymph node metastasis (2 papers, 2020 to 2024). "The abnormally high expression of CBX2 has been closely associated with the degree of malignancy, TNM stage, lymph node metastasis, and poor patient prognosis." (PMID 38355480, 2024).
neuroblastoma (2 papers, 2018 to 2021). Neuroblastoma (NB) is the most common solid, extracranial childhood tumor. "Three of those genes (CBX2, GJC1, LIMD2) are encoded on 17q, a chromosomal region invariably gained in high-risk neuroblastoma." (PMID 34638267, 2021).
neuroendocrine tumor (2 papers, 2015 to 2016). "Thus, the selective involvement of CBX2 and EZH2 in aggressive neuroendocrine tumors may not be restricted to NEPC." (PMID 25859291, 2015).
prostate tumor (2 papers, 2016 to 2018). "Increased CBX2 expression has also been correlated with lower overall survival, whereas CBX2 depletion negatively affects prostate tumor proliferation and progression." (PMID 29467492, 2018). "All these variables are themselves indicators of poor prognosis in patients; these data support the idea that elevated CBX2 expression is observed in aggressive prostate tumors." (PMID 26877821, 2016).
sarcoma (2 papers, 2019 to 2021). A usually aggressive malignant neoplasm of the soft tissue or bone. "In our present study, we observed elevated expression levels of CBX2 and found that CBX2 was associated with a poorer OS, thus indicating that this gene might be an independent prognostic factor for human sarcoma." (PMID 34046352, 2021). "Furthermore, all sarcoma patients were divided into high CBX2 expression group and low CBX2 expression group with the best cutoff chosen by xtitle software." (PMID 31150156, 2019). "Consistently, gene set enrichment analysis (GSEA) analysis showed that cell cycle and DNA replication were two overwhelmingly enriched genesets highly related with CBX2 overexpression, indicating that CBX2 might contribute to progression of sarcoma through regulating cell cycle and DNA replication." (PMID 31150156, 2019).
triple-negative breast carcinoma (2 papers, 2022). An invasive breast carcinoma which is negative for expression of estrogen receptor (ER), progesterone receptor (PR), and human epidermal growth factor receptor 2 (HER2). "CBX2 expression is elevated in triple-negative breast cancer (TNBC), for which there are few therapeutic options." (PMID 35884550, 2022).
viral infection (2 papers, 2019 to 2021). "We confirmed that the expression of CBX family proteins, especially Cbx2, was decreased in macrophages upon viral infection, and then we investigated the role of Cbx2 in the antiviral immune response." (PMID 30357595, 2019). "In this study, we observed that the expression of Cbx2, which is a coactivator of IFN-β, decreased during virus infection, although the underlying mechanism was unclear." (PMID 30357595, 2019). "Furthermore, polycomb chromobox (CBX) proteins, especially CBX2 were down-regulated in macrophage upon viral infection." (PMID 33509250, 2021).
benign prostate hyperplasia (1 paper, 2016). "First, we quantified the expression of CBX2 in LNCaP and C4-2 cell lines compared with benign prostate hyperplasia cells (BPH1)." (PMID 26877821, 2016).
cervical cancer (1 paper, 2025). A primary or metastatic malignant neoplasm involving the cervix. "To assess the potential role of CBX2 in cervical cancer, we further analyzed the associations between the CBX2 levels and patient survival and clinicopathological characteristics." (PMID 39793896, 2025). "In addition, a recent bioinformatics study reported that the CBX2 mRNA level was upregulated in cervical cancer and associated with cervical cancer pathological stages, which is consistent with our findings." (PMID 39793896, 2025). "In conclusion, our results identified a deregulated PRC1 component, CBX2 and established an association between CBX2, tumor progression, and resistance to DNA damage treatment, providing some evidence for future targeted therapy against CBX2 in cervical cancer." (PMID 39793896, 2025). "Gene set enrichment analysis revealed that the apoptosis was enriched in the cervical cancers with lower expression of CBX2 in the TCGA database." (PMID 39793896, 2025). "Our data revealed a previously undescribed deregulated PRC1 component CBX2 in cervical cancer and showed that CBX2 plays a critical role in cervical cancer proliferation and resistance." (PMID 39793896, 2025). "The 99 cervical cancers were divided into two groups (low CBX2 and high CBX2) according to their CBX2 IHC scores." (PMID 39793896, 2025). "We provided functional evidence demonstrating that CBX2 promoted cervical cancer cell proliferation." (PMID 39793896, 2025). "Flow cytometry revealed that the KD of CBX2 in cervical cancer cells resulted in decreased percentages of CD44+ population." (PMID 39793896, 2025). "The results of the Cell Counting Kit-8 assays showed that overexpression (OE) of CBX2 significantly promoted cell proliferation and that knockdown (KD) of CBX2 inhibited cell proliferation in cervical cancer cells." (PMID 39793896, 2025). "The expression of CBX2 in the cervical cancer cell lines HeLa and SiHa cells was efficiently manipulated by transfection with lentivirus carrying CBX2-expressing vectors or small interfering RNAs (siRNAs) targeting CBX2 mRNA." (PMID 39793896, 2025). "For validation, the CBX2 protein was detected via IHC analysis in 99 cervical cancers and 15 normal cervix tissues." (PMID 39793896, 2025). "One bioinformatics analysis study revealed a correlation between CBX2 mRNA expression and the pathological stage in cervical cancer." (PMID 39793896, 2025). "The CBX2 IHC score in cervical cancer was significantly greater than that in normal cervix, and the CBX2 signal in cervical cancer patients was predominantly located in tumor nests." (PMID 39793896, 2025). "Next, we performed functional experiments to determine the role of CBX2 in cervical cancer growth." (PMID 39793896, 2025). "Moreover, elevated CBX2 levels were significantly associated with age ≥ 45 years, lymph vascular invasion, lymph node metastasis, and tumor size ≥ 4 cm, indicating a tumor-promoting role of CBX2 in cervical cancer." (PMID 39793896, 2025). "Furthermore, CBX2 exhibited an antiapoptotic effect, which induced resistance to cisplatin and ionizing radiation in cervical cancer cells." (PMID 39793896, 2025). "In addition, colony formation assays revealed that CBX2 KD inhibited the clonogenic growth of cervical cancer cells treated with cisplatin." (PMID 39793896, 2025). "Nevertheless, the specific role of CBX2 in cervical cancer remains to be elucidated owing to the scarcity of both in vivo and in vitro experimental data and the correlation between CBX2 protein levels and clinicopathological characteristics in cervical cancer patients." (PMID 39793896, 2025). "Our results suggest that CBX2 emerged as an attractive therapeutic target in cervical cancer." (PMID 39793896, 2025). "Similarly, the results of the 5-ethynyl-2′-deoxyuridine (EdU) assays revealed notably greater percentages of proliferation cells in the cervical cancer cells overexpressing CBX2 than in the control cells." (PMID 39793896, 2025).
cervical cancer (continued). "This inhibitory peptide may be an option for targeting CBX2 therapy in cervical cancer." (PMID 39793896, 2025). "Therefore, we focused on the expression and functions of CBX2 in cervical cancer." (PMID 39793896, 2025). "Furthermore, these results also provide evidence that CBX2 might be a biomarker for cervical cancer prognosis and resistance." (PMID 39793896, 2025). "We found that CBX2, CBX4, and CBX8 presented notably increased expression, whereas PHC2, CBX6, and CBX7 presented decreased expression in cervical cancers." (PMID 39793896, 2025). "In this study, via bioinformation analysis and immunohistochemistry (IHC), we found that chromobox 2 (CBX2), rather than other PRC1 components, was significantly upregulated in cervical cancer and was associated with poor prognosis." (PMID 39793896, 2025). "In parallel, we investigated whether CBX2 contributes to radioresistance in cervical cancer cells or not." (PMID 39793896, 2025). "However, the functions of CBX2 and CBX7 are opposite in cervical cancer." (PMID 39793896, 2025). "In GSE63514, increased expression of CBX2, but not CBX4 or CBX8, was detected in cervical cancer patients compared with normal controls, and cervical precancerous lesions were observed." (PMID 39793896, 2025).
cervical squamous cell carcinoma (1 paper, 2025). A squamous cell carcinoma arising from the cervical epithelium. "In TCGA-cervical squamous cell carcinoma (CESC) cohort, CBX2 expression was positively correlated with the expression of the cancer stem cell markers SOX2 and ALDH1A1." (PMID 39793896, 2025).
clear-cell renal cell carcinoma (1 paper, 2023). "Our results are consistent with previous studies; we found that CBX2 is upregulated in breast and clear-cell renal cell carcinoma and patients with poor survival showed higher prognostic scores in both cancer types." (PMID 37489460, 2023).
embryonic carcinoma (1 paper, 2018). "To determine how CBX2 was regulated during neuronal differentiation, we took advantage of RA-induced human M17 cells and mouse P19 embryonic carcinoma cells as in vitro differentiation model." (PMID 29541019, 2018).
endometrial tumors (1 paper, 2022). "As for CBX1 and CBX2—we observed positive association with cancer stemness in liver, lung and endometrial tumors, while CBX4, CBX5, CBX6, and CBX8 exhibit rather weak correlation with cancer stemness in a tumor-specific manner." (PMID 36361869, 2022).
Infertility (1 paper, 2019). "Our study provided an excellent opportunity to identify genes surrounding CBX2 in the ovary and might contribute to the understanding of ovarian physiopathology causing infertility in women." (PMID 31745224, 2019).
liver cirrhosis (1 paper, 2022). "Two diagnostic models including SOCS2, LCAT, FTCD, KRT17, PBK, and CBX2 expression were proved to accurately separate HCC from normal and liver cirrhosis samples in this study." (PMID 36159831, 2022).
Miscarriage (1 paper, 2021). A pregnancy that ends at a stage in which the fetus is incapable of surviving on its own, defined as the spontaneous loss of a fetus before the 22th week of pregnancy. "In CG2, whose female partner suffered a miscarriage at 8 weeks, RNA analysis of spermatozoa identified 3 imbalanced genes involved in important DNA-binding transcription factor activity (RMI1) and embryogenesis (CBX2 and TGFB3)." (PMID 33877510, 2021).
ovarian disease (1 paper, 2019). "Several genes with diverse functions related to folliculogenesis, steroidogenesis and ovarian disease like PCOS, POF were found to be regulated directly and indirectly by CBX2 isoforms." (PMID 31745224, 2019).
peritoneal disease (1 paper, 2018). "Clinically, three of these patients had more extensive peritoneal disease suggesting that CBX2 could serve as a predictive marker of advanced disease, reinforcing the potential clinical significance of CBX2." (PMID 30478317, 2018).
renal cell carcinoma (1 paper, 2023). "According to CTRP drug sensitivity analysis, high level of CBX2, BLNK, PLK4, STIL and BIRC5 were associated with increased sensitivity to inhibitors of VEGF and MET pathways, which happened to be two crucial driver pathways of renal cell carcinoma." (PMID 37917664, 2023).
serous carcinoma (1 paper, 2024). "In a high-grade serous carcinoma immune-competent murine model, knockdown of CBX2 decreased tumor progression." (PMID 38984891, 2024). "Chromobox 2 (CBX2), an epigenetic reader and component of polycomb repressor complex 1, is highly expressed in >75% of high-grade serous carcinoma." (PMID 38984891, 2024).
uterine serous carcinoma (1 paper, 2020). "As to uterine serous carcinoma/uterine papillary serous carcinoma, the most common alterations were the high mRNA expression of all CDCA members, the amplification of CDCA5, CBX2 and CDCA8 and the missense mutation of CDCA2/7." (PMID 32913454, 2020).
cancer (54 papers, 2014 to 2026). A tumor composed of atypical neoplastic, often pleomorphic cells that invade other tissues. "CBX2 promotes cancer cell proliferation and tumor progression and is associated with the survival of high-grade serous ovarian cancer (HGSOC) patients." (PMID 40175347, 2025). "The cancer associated biological function of some were known little about, such as CBX2, CBX5, CDT1, TOPBP1 and RUNX2, but whose implication in cancer worth further exploration based on emerging evidences." (PMID 37917664, 2023). "Investigation of patient gene expression data sets also identified a potential role for CBX2 inhibiting RBL2 expression and, therefore, DREAM complex activity in other cancer types, again suggesting a common CBX2-associated oncogenic function." (PMID 35884550, 2022). "As an oncogenic gene, CBX2 is strongly associated with genome-scale DNA methylation in various types of cancer cells, which is a response to micro-environmental stresses, particularly oxidative stress." (PMID 36133439, 2022). "CBX2 is upregulated and implicated in the growth of a number of cancer types, suggesting it may be a potential therapeutic target." (PMID 35884550, 2022). "We also identified upregulation of CBX2 in cancer tissues and its association with HCC stage." (PMID 36566204, 2022). "CBX2 overexpression has been found implicated in promoting cancer cell proliferation." (PMID 35681235, 2022). "Beyond EZH2, overexpression of another Polycomb protein in PRC1, chromobox homolog protein 2 (CBX2), is also associated with poor survival by maintaining CSCs, which might be an emerging approach targeting Polycomb proteins that could be used in cancer therapy." (PMID 35509102, 2022). "Background and Objectives: Chromobox protein homolog 2 (CBX2), a member of the polycomb group of proteins that plays a role in chromatin remodeling, has been associated with multiple types of cancer." (PMID 42195095, 2026). "In Hematological malignancies, CBX2 is often overexpressed and plays a crucial role in driving cancer cell progression." (PMID 40175347, 2025). "Our data show that CBX2 facilitates antiapoptotic effect when cancer cells are exposed to DNA damage." (PMID 39793896, 2025). "Prior studies have demonstrated that CBX2 facilitates cancer cell proliferation, enhances cancer stemness, and suppresses apoptosis." (PMID 39793896, 2025). "This interaction increases CBX2 expression, ultimately promoting cancer cell proliferation, migration, and invasion." (PMID 40175347, 2025). "The previous studies found that CBX2 acts as a transcription factor regulating numerous cell functions, which means CBX2 exerts important role in cancer development." (PMID 38355480, 2024). "A recent study revealed that CBX2 inhibits cancer cell proliferation and invasion by regulating the Akt/PI3K pathway." (PMID 38355480, 2024). "CBX2 is dysfunctional in many cancers and plays a key role in epigenetic regulation of cancer development and growth-related genes." (PMID 39114365, 2024). "Similar to our study, there is increasing evidence that overexpression and amplification of CBX2 were substantially related to proliferation, metastasis and poor prognosis in a variety of cancers." (PMID 38702698, 2024). "Compared with siControl, siCXCL1/8 spheroids showed a significant reduction in macrophage infiltration, suggesting cancer cell CBX2-mediated regulation of CXCL1/8 expression contributes to differential macrophage infiltration." (PMID 38984891, 2024). "CBX2 has been demonstrated to impact the development and advancement of various cancers, albeit it has received limited attention in relation to HCC." (PMID 37980163, 2023). "CBX2 is known to modulate genes that regulate cell cycle progression, apoptosis, and DNA damage response, leading to uncontrolled proliferation of cancer cells." (PMID 38030604, 2023). "Chromobox protein homolog 2 (CBX2) has been identified as a multifaceted player in the progression of aggressive cancers." (PMID 38030604, 2023).